PCK1 (phosphoenolpyruvate carboxykinase 1)
Diseases named in the same sentence as PCK1 in open-access papers (continued):
Sharing a sentence is not in itself a finding about the gene and the disease.
tumor (continued). "PCK1 overexpression has been used to reprogram tumor-reactive T cells and enhance anti-tumor T cell responses." (PMID 32762776, 2020). "Down-regulated genes contain markers enriched in mature hepatocytes (Tat, Cyp7a1, Apoa5, Pck1, Cyp3a11, Mup3 or Acsl1) and tumor suppressors (Lect2, Wfdc17 or Efemp1)." (PMID 32372053, 2020). "In tumor cells of various origins, PCK1 or PCK2 have been found to mediate abbreviated gluconeogenesis, especially under conditions of glucose deprivation, thus contributing to anabolic metabolism." (PMID 32777161, 2020). "Compared with parental PLC/PRF/5 cells, PCK1-KO significantly promoted orthotopic tumor formation in mice." (PMID 30717766, 2019). "In this study, we explored the potential role of PCK1 in the suppression of cellular proliferation and tumor growth in HCC." (PMID 30717766, 2019). "Previous studies have indicated that PCK1 expression is significantly lower in tumor tissues than in normal liver tissues and that downregulated PCK1 expression correlates with poor prognosis." (PMID 30717766, 2019). "Elevated expression of PCK1 has been reported to benefit tumor growth in certain cancers by maintaining anabolic metabolism." (PMID 30619751, 2018). "Overexpression of PCK1 significantly reduced the growth rate of MHCC-97H tumor growth compared with the mock and GFP control group by measuring tumor volume every 4 days (*P < 0.05, AdPCK1 group vs. AdGFP group)." (PMID 30619751, 2018). "The data showed that PCK1 expression was significantly lower in tumor tissues than in normal liver tissues." (PMID 30619751, 2018). "Immunohistochemical staining showed that PCK1 expression levels were significantly lower in HCC than in para-tumor tissues (P < 0.01)." (PMID 30619751, 2018). "Specifically, TFAM knockdown, like ddC treatment, sequentially causes mtDNA depletion, calcium-mediated mitochondrial retrograde signaling, CFAP65 induction, and PCK1 induction, resulting in polygonalization and hypoproliferation of tumor cells." (PMID 29259235, 2017). "al. discovered that tumor-reactive T cells can be metabolically rewired through phosphoenolpyruvate carboxykinase 1 (PCK1) overexpression." (PMID 26885366, 2016). "Since apoptosis was a crucial mechanism through which cetuximab induced tumor cell death 30, MT1E and MT2A expression might correlate with enhanced drug sensitivity, while PCK1 and TGFBI expression might be linked to resistance." (PMID 40959565, 2025). "Furthermore, PCK1-overexpressing T cells restricted tumor growth and prolonged the survival of melanoma-bearing mice." (PMID 40617808, 2025). "Furthermore, research has identified phosphoenolpyruvate carboxykinase 1 (PCK1) as a critical regulator of tumor metabolism and proliferation." (PMID 40051496, 2025). "Based on the results above, we propose that further increasing PCK1 expression could exert tumor-promoting activity." (PMID 38670942, 2024). "PCK1 inhibits Warburg effect-related pathways in hepatorenal cell carcinoma by preventing glucose from entering the glycolytic pathway, thereby inhibiting tumor cell growth and promoting tumor cell death." (PMID 39578429, 2024). "Phosphoenolpyruvate carboxykinase 1 (PCK1) is known to be an enzyme that limits the rate of gluconeogenesis, but its role in both tumor metabolism and GC progression is unknown." (PMID 38737262, 2024). "Interestingly, studies have used clinical compounds (nilotinib and lapatinib) that also target PCK1 to inhibit tumor growth in AR-negative and NE-like PCa cell models." (PMID 39578429, 2024). "Finally, glyconeogenesis from Gln has also been reported to occur via PCK2 in some tumor cells and neutrophils and via PCK1 in murine memory CD8+ T cells." (PMID 39424955, 2024). "However, malignant hepatocytes inhibit gluconeogenesis by downregulating PCK1 in favor of tumor glycolysis." (PMID 39578429, 2024). "It is controversial whether PCK1 plays an oncogenic or tumor suppressor function in various human cancers." (PMID 38791477, 2024).
tumor (continued). "However, in HCC, PCK1 is dysregulated by multiple oncogenes, oncogenic signaling regulation, and tumor metabolism." (PMID 39578429, 2024). "Furthermore, when PCK1-overexpressing tumor-specific T cells were injected back into tumor-bearing mice, a stronger anti-tumor immunotherapy effect was obtained than that achieved with control cells." (PMID 39578429, 2024). "Given the role of PEPCK (PCK1 or PCK2) in regulating antioxidants in tumor cells, we investigated whether IGF2BP3lac influences redox homeostasis by modulating PCK2 expression." (PMID 39450426, 2024). "The findings of the present study hint at the possibility that PCK1 could be considered as an important tumor-promoting protein and a potential therapeutic target of UVM." (PMID 38670942, 2024). "Moreover, restoring gluconeogenesis by overexpressing PCK1 or TEF through miR-4477b inhibition significantly inhibited tumor cell proliferation, colony formation, and induced cell apoptosis in vitro." (PMID 37553601, 2023). "Evidence of the significance of PCK1 in tumor development and progression is accumulating." (PMID 37062825, 2023). "Knockout of PCK1 partly countered the tumor-inhibiting effect of knockout of A2B1 on HCC." (PMID 38017546, 2023). "PCK1 can induce tumor cell proliferation and metastasis by disrupting cellular metabolism." (PMID 37062825, 2023). "As the key enzyme catalyzing the conversion of OAA into PEP, PCK1 overexpression could elevate PEP levels in T cells under glucose-limited conditions to enhance the anti-tumor effect of tumor-specific CD4+ T cells." (PMID 37250903, 2023). "Therefore, tumor diameter, tumor stage, lymph node metastasis, PCK1 expression, and tumor differentiation were entered into a multivariate prognostic Cox regression model." (PMID 37062825, 2023). "PCK1 was expressed at significantly lower levels in CRC than in non-tumor specimens." (PMID 37062825, 2023). "PCK1 can also induce tumor cell proliferation by participating in glycolipid conversion." (PMID 37062825, 2023). "On the contrary, in some cancers, such as liver and kidney cancer, tumor cells expressing key enzymes of gluconeogenesis, including PCK1, FBP, and G6P, can promote the whole gluconeogenesis pathway to produce glucose, which, in turn, inhibits the glycolytic pathway." (PMID 37064872, 2023). "Furthermore, we also predicted that the small-molecule compound, mersalyl, would target PCK1 which induces the VEGF gene in invasive tumor cases." (PMID 36193307, 2022). "Interestingly, binding to the promoter region was higher in NFYAv2OE cells than in wild-type cells, supporting that NFYAv2 predominantly regulates PCK1 transcription, thereby contributing to its anti-tumor effects." (PMID 36092708, 2022). "Therefore, the role of PCK1 in the drug resistance process of other tumor cells needed to be further revealed, and the observation cycle also needs to be optimized to explore the specific functions of PCK1 from a long-term and objective perspective." (PMID 36700470, 2022). "Our study revealed that PCK1 is an important antitumor mRNA and inhibitor of tumor progression." (PMID 36193307, 2022). "This means that the PCK1 gene can be a tumor prognostic marker for mCRC." (PMID 36193307, 2022). "Their data provided proof of concept that adoptively transferred tumor-infiltrating lymphocytes with overexpression of phosphoenolpyruvate carboxykinase 1 (PCK1) and greater levels of PEP have enhanced antitumor response and are immune from glucose-deprivation conditions." (PMID 35968786, 2022). "Furthermore, several studies have reported that the gluconeogenic enzyme PCK1 is suppressed in cancer tissues and functions as a tumor suppressor in gluconeogenic organs such as the liver and kidney." (PMID 36092708, 2022). "To test whether PCK1 can exert similar tumor-promoting activity in vivo, we utilized a xenograft mouse model." (PMID 34620839, 2021). "PCK1 is upregulated in human melanoma and colon carcinoma, and promoted tumor growth." (PMID 34650217, 2021).
tumor (continued). "Furthermore, we observed that tumor metastasis rate was inversely proportional to the expression of PCK1 in HCC." (PMID 34650217, 2021). "Other studies, however, proposed a potential tumor-suppressive function of PCK1." (PMID 34620839, 2021). "Furthermore, Akt-mTOR inactivation was detected in PCK1 shRNA-expressing PANC-1 xenograft tumor tissues." (PMID 34620839, 2021). "Collectively, these findings indicate that PCK1 inhibits tumor growth both in vitro and in vivo." (PMID 30717766, 2019). "The effect of PCK1 on tumor growth was examined in xenograft implantation models." (PMID 30717766, 2019). "Moreover, pAMPK and p27Kip1 expression was markedly increased in tumor tissues exogenously expressing PCK1, as evidenced by western blotting and IHC." (PMID 30717766, 2019). "Similarly, PCK1 downregulation has been observed in other cohorts of HCC, where restoration of its expression leads to tumor suppression, indicating that PCK1 acts as a tumor suppressor in HCC." (PMID 30717766, 2019). "Notably, all the genes associated with the tumor stage except GBA3 and PCK1 were independent predictors for OS in at least one of the two data sets." (PMID 31847435, 2019). "Furthermore, tumor volume and weight were notably reduced in the PCK1-OE group compared with the GFP control group." (PMID 30717766, 2019). "For instance, circSMAD2 inhibits the migration, invasion, and EMT of HCC cells by targeting miR-629 and markedly associates with the differentiation degree; circC3P1 acts as a tumor suppressor via enhancing PCK1 expression by sponging miR-4641 to inhibit HCC growth and metastasis." (PMID 31187026, 2019). "Consistent with previous studies, our data suggest a tumor-suppressor function of PCK1 in HCC." (PMID 30619751, 2018). "Our results implicate that PCK1 acts as a tumor suppressor in HCC and combination therapy of sorafenib and TXNRD1 inhibitors may be a novel strategy for HCC treatment." (PMID 30619751, 2018). "In addition, the average tumor size was smaller in the PCK1-overexpression group than that in the control group." (PMID 30619751, 2018). "Moreover, PCK1-overexpressing T cells restricted tumor growth and prolonged the survival of melanoma-bearing mice." (PMID 27774525, 2016). "PC, ACO1, IDH2 and PCK1 and were overexpressed in tumor samples from liver metastases only." (PMID 22412968, 2012). "However, loss of PCK1 in macrophages contributes to metabolic reprogramming and M1 polarization of macrophages and increases the expression of the proinflammatory cytokines(IL-6, IL-1β, TNF-αand so on), leading to anti-tumor effects." (PMID 39578429, 2024). "The different tissues of tumor origin and the autonomous energy demand of tumors for proliferation and metastasis lead to metabolic heterogeneity, which may be one of the key reasons why PCK1 has different functions in different organs." (PMID 39578429, 2024). "Moreover, PCK1 also promotes protein kinase activity to activate sterol regulatory element binding proteins (SREBPs), resulting in the transcription of lipogenesis genes and promoting the rapid proliferation of tumor cells." (PMID 39262325, 2024). "Interestingly, PCK1 knockout partially counteracted tumor inhibition by hnRNPA2B1 knockout in mice." (PMID 38017546, 2023). "Although PCK1 expression in tumours may not be very high in some publicly-available database such as the Human protein atlas, it must be acknowledged that PCK1 expression can be dynamic in the cells and can become increasingly expressed when the tumour experiences a low glucose condition." (PMID 37407566, 2023). "These clinical data suggest that high PCK1 expression may inhibit tumor proliferation." (PMID 37062825, 2023). "Therefore, PCK1 may be a promising therapeutic target involved in metabolic adaptation to increase effector functions of tumor-specific T cells in glucose-deprived environments." (PMID 37250903, 2023). "We further ascertained whether PCK1-induced tumor suppression could be rescued by S100A11." (PMID 37166978, 2023).
tumor (continued). "However, PCK1 has contrasting effects on tumorigenesis in different tumor types." (PMID 30717766, 2019). "These previous findings are consistent with our data indicating that augmenting gluconeogenesis, probably by upregulation of PCK1, deleteriously affects cancer cell proliferation, although it remains to be investigated whether gluconeogenesis is involved in the tumor suppressor activity of PCK1." (PMID 29259235, 2017). "Furthermore, the switch from OXPHOS to glycolysis has also been observed in tumor-repopulating cells (TRCs), a stem cell-like subpopulation with highly invasive phenotypes that are responsible for tumor regeneration, by regulating phosphoenolpyruvate carboxykinase 1 (PCK1) and PCK2." (PMID 40617808, 2025). "Energy metabolism favours oxidative phosphorylation and the tricarboxylic acid (TCA) cycle (OGDHL, PCK1, ACO1, FH) over glycolysis, limiting tumour growth." (PMID 41007296, 2025). "Under low-glucose conditions, over expression of PCK1 promotes TCA cycle cataplerosis, energy crisis, and oxidative stress, thereby inducing HCC cell death and exerting a tumor-suppressive effect." (PMID 39980550, 2025). "For example, expressing a mutant, constitutively active form of phosphoenolpyruvate carboxykinase 1 (PCK1) can enhance T-cell mitochondrial metabolism and improve their anti-tumor function in low-glucose conditions." (PMID 41154636, 2025). "Overall, we discussed that PCK1 is downregulated in tumors of gluconeogenic organs (HCC and RCC) and has anti-tumor effects." (PMID 39578429, 2024). "Phosphoenolpyruvate carboxykinase 1 (PCK1) is the first rate-limiting enzyme of gluconeogenesis, and has an anti-tumor effect in liver tumor." (PMID 38550587, 2024). "While PCK1 is the dominant form of PCK in the liver, the active and functional form of PCK in cancer cells is dependent on tumor types." (PMID 39193344, 2024). "Mechanistically, PCK1 destabilizes lactate dehydrogenase A (LDHA) through post-translational regulation, suppressing the Warburg effect and tumor progression." (PMID 39578429, 2024). "PCK1 acts as a protein kinase to activate SREBP1 to increase lipid synthesis and promote tumor growth in NSCLC." (PMID 39578429, 2024). "The silencing of the PCK1 gene by hsa-miR-27a-3p may trigger a metabolic reprogramming of cancer cells which would make them take over and become more resistant and invasive when under nutrient starvation, which is a typical situation in the tumor microenvironment." (PMID 38791477, 2024). "We observed major genetic alterations in PCK1, SHC2, and KRT6B, emphasizing the role of these genes in tumor behavior modification as well as the response to treatment." (PMID 38791477, 2024). "In this study, we demonstrate that PCK1 is expressed at low levels in CRC tissues, while its overexpression suppresses CRC cell growth, and silencing PCK1 promotes tumor proliferation." (PMID 37062825, 2023). "Overexpression of metabolic enzymes in T cells, such as phosphoenolpyruvate carboxykinase 1 (PCK1), has been shown to bolster T-cell functions and enhance the efficacy of adoptive T-cell therapy in mouse tumor models." (PMID 37305096, 2023). "Immunohistochemical staining confirmed that the expression level of PCK1 was lower in the tumor tissues formed in A2B1 and PCK1 double knockout mice than A2B1 sgRNA group." (PMID 38017546, 2023). "IHC analysis showed PCK1 and ATG5 was up-regulated, while P62 and p-UBAP2L Ser454 expression was down- regulated in PCK1-OE tumor tissues." (PMID 37062825, 2023). "In particular, most of the amplified genes are involved in proliferation and tumour progression in PDAC, such as AURKA, HRH3, MIR646, MRGBP, PCK1, PMEPA1, SLCO4A1-AS1, SOX18, and TNFRSF6B." (PMID 36289850, 2022). "Still, more research is warranted to understand the role of PCK1 and PCK2 in different tumor entities." (PMID 33540663, 2021). "H&E staining for sections indicated that more Pck1-LKO mice had metastatic tumor nodules and larger size of tumor nodules in lung." (PMID 34650217, 2021).